ADORA3 (adenosine A3 receptor)
Diseases named in the same sentence as ADORA3 in open-access papers (continued):
Sharing a sentence is not in itself a finding about the gene and the disease.
liver cancer (5 papers, 2013 to 2025). An epithelial or non-epithelial malignant neoplasm that arises from the liver. "In summary, these experiments employing human-derived PDOs further suggest combining an ADORA3 agonist with an HDACi as a new option to target liver cancer." (PMID 39911497, 2025). "Our findings highlight the importance of understanding ADORA3’s role not only in liver cancer but also in normal liver physiology, potentially guiding the optimization of ADORA3-targeted therapies." (PMID 39911497, 2025). "However, further data are required to clarify ADORA3 expression patterns in liver cancer, mechanisms of action, and the potential for combination therapies to inform patient selection for future clinical trials." (PMID 39911497, 2025). "However, to select relevant patient groups in further clinical trials, more data are needed to characterize ADORA3 and cellular responses after receptor stimulation in liver cancer." (PMID 39911497, 2025). "Therefore, HDAC inhibition in combination with stimulation of ADORA3 might be an attractive new combined drug therapy for the treatment of liver cancer." (PMID 39911497, 2025). "In conclusion, the further development of the concept of ADORA3 activation and inhibition of HDACs in a clinical study to treat liver cancer seems to be reasonable and promising, even without evidence of additional preclinical animal models." (PMID 39911497, 2025).
bladder cancer (4 papers, 2018 to 2025). "Over expression of ADORA3 in human bladder cancer cells had similar effects to treatment with Cordyceps extract, whereas depletion of ADORA3 abrogated the effect of Cordyceps extract containing cordycepin as a major component." (PMID 30287757, 2018). "Few studies had reported that the six genes (TBXAS1, GYPC, HPGDS, GAB3, ADORA3, and FOLR2) had strong correlation with bladder cancer." (PMID 36275756, 2022).
essential hypertension (4 papers, 2016 to 2024). Hypertension that presents without an identifiable cause. "We observed the adenosine A3 receptor expression was different between tissue types and with hypertension." (PMID 26907173, 2016). "In the present study, we have demonstrated that alterations in adenosine A3 receptor expression might contribute to essential hypertension." (PMID 26907173, 2016). "This study was designed to investigate the expression of adenosine A3 receptor in cardiovascular tissues and a range of blood vessels from Wistar and spontaneously hypertensive rats (SHRs)—a well-established model of hypertension, and to determine whether they are altered with EH." (PMID 26907173, 2016).
pneumonia (4 papers, 2023 to 2025). An acute, acute and chronic, or chronic inflammation focally or diffusely affecting the lung parenchyma, caused by an infection in one or both of the lungs (by bacteria, viruses, fungi, or mycoplasma.). "In Baladi goats with pneumonia and healthy control group, PCR-DNA sequencing revealed SNPs linked to pneumonia susceptibility and resistance in immunological genes (SLC11A1, CD-14, CCL2, TLR1, TLR7, TLR8, TLR9, defensin, SP110, SPP1, BP1, A2M, ADORA3, CARD15, IRF3, and SCART1)." (PMID 40221769, 2025). "The immune genes’ mRNA levels in goats (SLC11A1, CD-14, CCL2, TLR1, TLR7, TLR8, TLR9, defensin, SP110, SPP1, BP1, A2M, ADORA3, CARD15, IRF3, and SCART1) varied between the healthy and infected goats with pneumonia." (PMID 40711280, 2025). "Through PCR-DNA sequencing in Baladi goats with and without pneumonia, SNPs linked to pneumonia susceptibility and resistance were discovered in the immunological (SLC11A1, CD-14, CCL2, TLR1, TLR7, TLR8, TLR9, defensin, SP110, SPP1, BP1, A2M, ADORA3, CARD15, IRF3, and SCART1) genes." (PMID 40711280, 2025). "The levels of immunological genes (SLC11A1, CD-14, CCL2, TLR1, TLR7, TLR8, TLR9, defensin, SP110, SPP1, BP1, A2M, ADORA3, CARD15, IRF3, and SCART1) vary in goats with and without pneumonia." (PMID 40221769, 2025). "Real-time PCR was conducted to quantify the expression levels of immunological markers (SLC11A1, CD-14, CCL2, TLR1, TLR7, TLR8, TLR9, β defensin, SP110, SPP1, BP1, A2M, ADORA3, CARD15, IRF3, and SCART1) in Baladi goats with and without pneumonia resistance." (PMID 36977224, 2023).
cardiac ischemia (3 papers, 2022 to 2023). "ADORA3 (Adenosine A3 Receptor) which encodes a protein that belongs to the family of adenosine receptors mediates a sustained cardioprotective function during cardiac ischemia." (PMID 36275756, 2022).
Cognitive impairment (3 papers, 2020 to 2024). Abnormal cognition is characterized by deficits in thinking, reasoning, or remembering. "On this basis, we explored the role of ADORA3 antagonist in VaD and demonstrated that ADORA3 antagonist also has therapeutic effects on chronic ischemia‐induced cognitive impairment and WMI." (PMID 38715283, 2024). "We revealed that ADORA3 antagonist can ameliorate WMI and cognitive impairment after BCAS by improving Mertk‐mediated microglial phagocytosis to myelin debris, and Mertk‐mediated microglial phagocytosis is promoted by the activation of cAMP/PKA/p‐CREB pathway." (PMID 38715283, 2024). "ADORA3 antagonist promotes microglial phagocytosis to myelin debris by facilitating cAMP/PKA/p‐CREB pathway and thereby ameliorates WMI and cognitive impairment in BCAS mice." (PMID 38715283, 2024). "We observed the effects of ADORA3 antagonist on WMI and cognitive impairment in BCAS mice and expect to provide a new therapeutic strategy to alleviate VaD." (PMID 38715283, 2024). "ADORA3 antagonist promotes the expression of Mertk and Axl in microglia by facilitating cAMP/PKA/p‐CREB pathway, enhances microglial phagocytosis to myelin debris, and improves white matter injury and cognitive impairment in BCAS mice." (PMID 38715283, 2024).
diabetic nephropathy (3 papers, 2016 to 2021). "At present, no previous studies have related the levels of this enzyme with adenosine signaling in diabetic nephropathy, but it is suggested that the use of the ADORA3 antagonist could have a major role on caspase 1 activation, which is a necessary event in the generation of interleukins." (PMID 31540220, 2019). "It was previously demonstrated that the use of ADORA3 antagonists have anti-inflammatory effects, however the renoprotective properties of the use of these antagonists in diabetic nephropathy has been suggested, but not mechanistically understood." (PMID 31540220, 2019).
dilated cardiomyopathy (3 papers, 2018 to 2025). Cardiomyopathy which is characterized by dilation and contractile dysfunction of the left and right ventricles. "Studies in murine models have revealed that slight overexpression of ADORA3 enhances cardioprotection with no adverse effects, but a six fold overexpression in mice could result in dilated cardiomyopathy." (PMID 29955603, 2018). "While CXCL9, CXCL10, and CXCL11 belong to the chemokine family, CX3CR1, ADORA3 and SAA1 have not been reported in dilated cardiomyopathy, and further research is needed." (PMID 35618744, 2022).
lung disease (3 papers, 2022 to 2025). "This suggests a potential involvement of ADORA3 in the processes of fibrotic lung disease." (PMID 36056346, 2022).
renal fibrosis (3 papers, 2016 to 2020). A final common manifestation of a wide variety of chronic kidney diseases characterized by glomerulosclerosis and tubulointerstitial fibrosis. "However, our results are in line with more recent studies implicating the adenosine A3 receptor in renal fibrosis." (PMID 33238361, 2020). "This downregulation could be an important mechanism to control adenosine A3 receptor-mediated renal fibrosis." (PMID 33238361, 2020). "Furthermore, the ADORA3 antagonism has the potential to block renal fibrosis in diabetic rats, since the distribution of the pro-fibrotic marker α-SMA was markedly decreased at the renal level, mainly at the tubulointertitium." (PMID 31540220, 2019).
autoimmune disease (2 papers, 2015 to 2022). A disorder resulting from loss of function or tissue destruction of an organ or multiple organs, arising from humoral or cellular immune responses of the individual to their own tissue constituents. "At least seven of these are involved in autoimmune diseases or immune cell function: Ptpn22, Adora3, Rbm15, Lrig2, Cd53, Nras, and a cluster of six chitinase-like genes." (PMID 26438525, 2015). "In addition, ADORA3 is overexpressed in inflammation and up-regulated in peripheral blood mononuclear cells of autoimmune diseases." (PMID 36056346, 2022).
lymphoma (2 papers, 2012 to 2025). A malignant (clonal) proliferation of B- lymphocytes or T- lymphocytes which involves the lymph nodes, bone marrow and/or extranodal sites. "Of these, adenosine might be through binding to adenosine A3 receptors (A3-AR) to decrease the telomeric signal, resulting in G0/G1 arrest of lymphoma cell." (PMID 22454661, 2012).
acute pancreatitis (1 paper, 2013). An acute inflammatory process that leads to necrosis of the pancreatic parenchyma. "The aim of this study is (Ed note: Purpose statements should be in present tense) to evaluate the effects of the adenosine A3 receptor agonist on the course of sodium taurocholate-induced experimental acute pancreatitis (EAP)." (PMID 23625750, 2013). "The purpose of this experimental study is to determine the effects of IB-MECA, the adenosine A3 receptor agonist, on histopathological changes and amylase as well as lipase activity in sodium taurocholate-induced experimental acute pancreatitis." (PMID 23625750, 2013).
autism (1 paper, 2013). Persistent deficits in social interaction and communication and interaction as well as a markedly restricted repertoire of activity and interest as well as repetitive patterns of behavior. "We examined whole exome sequence data from 339 cases and pair-matched controls of European ancestry generated by the NIH ARRA Autism Sequencing Consortium for the presence of functional variants at ADORA3 (see methods for exclusion criteria)." (PMID 23953133, 2013). "To test whether common alleles at ADORA3 contribute to ASD risk, we genotyped a sample consisting of 958 autism families using four SNPs representing common haplotypes that span the ADORA3 locus." (PMID 23953133, 2013).
brain tumors (1 paper, 2024). "Finally, we can indicate that TGFB1 is a marker of poor prognosis in brain tumors and correlates with the expression of HIFs, ectonucleotidases, and the ADORA3 gene involved in purinergic signaling in GB." (PMID 38794149, 2024).
chronic hepatitis (1 paper, 2017). An active inflammatory process affecting the liver for more than six months. "Other negative T cell inhibitory molecules, including natural killer cell receptor CD244, lymphocyte-activation gene 3 (LAG-3), T cell immunoglobulin domain and mucin domain-3 (Tim-3), CD160, and adenosine A3 receptor (A3AR) are related to T cell dysfunction in chronic hepatitis and HCC." (PMID 28703774, 2017).
cystic fibrosis (1 paper, 2024). Autosomal recessive disorder caused by pathogenic variants in the CFTR gene (cystic fibrosis transmembrane conductance regulator), which encodes a chloride and bicarbonate channel expressed in epithelial cells, and follow the diagnosis criteria. "Anti-inflammatory responses to iPR treatment have been documented in Chinese hamster ovary (CHO) cells where they are mediated through binding to adenosine A3 receptor and in cystic fibrosis cell lines via inhibition of NFκB and STAT3 pathways." (PMID 38932119, 2024).
dementia (1 paper, 2024). Loss of intellectual abilities interfering with an individual's social and occupational functions. "Furthermore, the expression of ADORA3 mRNA was found to be higher in the frontal and temporal lobes of VaD patients compared to non‐dementia patients, and the ROC curve also demonstrated good diagnostic value." (PMID 38715283, 2024).
endothelial dysfunction (1 paper, 2016). In vascular diseases, endothelial dysfunction is a systemic pathological state of the endothelium (the inner lining of blood vessels) and can be broadly defined as an imbalance between vasodilating and vasoconstricting substances produced by (or acting on) the endothelium. "Variants in adenosine A1 receptor (ADORA1) were associated with endothelial dysfunction in the entire cohort, whereas variants in adenosine A3 receptor (ADORA3) and lipoprotein(a) (LPA) had the strongest associations with increased risk of endothelial dysfunction in women only." (PMID 27932996, 2016).
gastric cancer (1 paper, 2025). A primary or metastatic malignant neoplasm involving the stomach. "Unlike the adenosine A1 receptor, hypoxic conditions do not affect the expression of the adenosine A3 receptor.In the context of the stomach, there are no relevant studies showing that Adora3 is associated with the prognosis of gastric cancer." (PMID 41346607, 2025).
glomerulosclerosis (1 paper, 2020). A hardening of the kidney glomerulus caused by scarring of the blood vessels. "The expression and function of the adenosine A3 receptor in kidney has seldom been studied, but it has been suggested to delay the development of glomerulosclerosis, due to mesangial cell apoptosis." (PMID 33238361, 2020).
HCMV infection (1 paper, 2017). "Network analysis of the differentially expressed genes in cord DCs, revealed among the downregulated genes after 16 h of HCMV infection several GPCRs with pro-inflammatory response function (ADORA3, ARRB1, C5AR1, CXCR4, GPR34, GPR183, GRK3, and RGS18)." (PMID 28993767, 2017).
head and neck squamous cell carcinoma (1 paper, 2020). A squamous cell carcinoma that arises from any of the following anatomic sites: lip and oral cavity, nasal cavity, paranasal sinuses, pharynx, larynx, and salivary glands. "Interestingly, it has also been reported that CD73 promotes invasion and metastasis of head and neck squamous cell carcinoma (HNSCC) by stimulating the adenosine A3 receptor." (PMID 33187081, 2020).
hepatoblastoma (1 paper, 2024). Hepatoblastoma (HB) is a malignant hepatic tumor and is the most common pediatric liver cancer. "In detail, we performed cell-line drug response and viability assays on the human HEPG2 hepatoblastoma cell line for CGS-15943, an ADORA2A and ADORA1 inhibitor, which is reported to act against multiple adenosine receptors, and MRS-1220, an ADORA3 and ADORA2B inhibitor." (PMID 38723607, 2024).
infarct (1 paper, 2011). "Exogenous ADORA1 and ADORA3 agonists reduced cardiac infarct size and improved functional recovery in isolated heart models." (PMID 21603615, 2011).
kidney damage (1 paper, 2019). "In this study, we demonstrated that treatment with an ADORA3 antagonist provides a renoprotective effect during the early stages of kidney damage in STZ-induced diabetic rats by decreasing the proinflammatory cytokines IL-1β and IL18." (PMID 31540220, 2019).
liver cirrhosis (1 paper, 2025). "The first and so far only phase II study with HCC included patients with liver cirrhosis CHILD B without any stratification concerning ADORA3 due to the hypothesis that a general overexpression of ADORA3 receptors is present in HCC." (PMID 39911497, 2025).
mental disorder (1 paper, 2018). A disease that has its basis in the disruption of mental process. "Specially, the crucial neuroactive ligand-receptor interaction pathway has been applied into the analysis of mental disorders, which is regulated by 25 potential targets (ADORA1, ADORA2A, ADORA3, etc.)." (PMID 30127739, 2018).
migraine (1 paper, 2022). "The involvement of adenosine A3 receptor in migraine has not been further investigated, however, adenosine A3 receptor agonist exhibited anti-nociceptive properties in models of chronic pain in rats and mice." (PMID 35382738, 2022).
neuroblastoma (1 paper, 2022). Neuroblastoma (NB) is the most common solid, extracranial childhood tumor. "Interestingly, between human and murine neuroblastoma cells, differences in the ADORA2B and ADORA3 expression pattern can also be observed." (PMID 35216410, 2022).
pancreatitis (1 paper, 2013). Inflammation of the pancreas. "However, the role of adenosine A3 receptor agonist in pancreatitis has not been well established." (PMID 23625750, 2013).
Parkinson disease (1 paper, 2025). A progressive degenerative disorder of the central nervous system characterized by loss of dopamine producing neurons in the substantia nigra and the presence of Lewy bodies in the substantia nigra and locus coeruleus. "This suggests that ADORA3 may play a role in Parkinson’s disease and has potential as a therapeutic target." (PMID 40362672, 2025).
Peritoneal Fibrosis (1 paper, 2023). Disorder characterized by a wide range of structural changes in PERITONEUM, resulting from fibrogenic or inflammatory processes. "Among them, MMP2, BAX, ADORA3, HIF1A, PIM1, CA12, and ALOX5 exhibited higher expression in the peritoneum with encapsulating peritoneal sclerosis compared with those in the control, which might be crucial targets of baicalein against peritoneal fibrosis." (PMID 37266145, 2023).
promyelocytic leukaemia (1 paper, 2021). "Flow cytometry has been used to quantify the specific binding of an adenosine A3 receptor agonist (MRS5218) in human promyelocytic leukaemia cells that was displaceable by unlabelled adenosine A3 receptor selective antagonist." (PMID 33506623, 2021).
vascular dementia (1 paper, 2024). A degenerative vascular disorder affecting the brain. "Adenosine A3 receptor (ADORA3) belongs to the adenosine receptor families and the role of ADORA3 in vascular dementia (VaD) is largely unexplored." (PMID 38715283, 2024).